MTOR (mechanistic target of rapamycin kinase)
Diseases named in the same sentence as MTOR in open-access papers (continued):
Sharing a sentence is not in itself a finding about the gene and the disease.
hearing loss (8 papers, 2016 to 2025). "The pharmacological modulation of the mTOR pathway using rapamycin has been shown to promote hair cell differentiation and delay age-related hearing loss, suggesting possible repurposing routes." (PMID 40724871, 2025). "Recent study reported that a low dose intraperitoneal injection of sirolimus (mTOR inhibitor) attenuated age-related hearing loss by decreasing the mTORC1, while high dose of sirolimus caused severe hearing loss by decreasing mTORC2/Akt." (PMID 36661507, 2022). "Among these genes, ATG5, ATG7 showed the highest node scores in the mild hearing loss group, whereas MTOR, BECN1 showed the highest node scores in the severe hearing loss group." (PMID 35463035, 2022). "Oleic acid, linoleic acid, and palmitic acid are known to activate autophagy through mTOR-dependent or -independent pathways, and autophagy can improve inner ear cell survival by reducing oxidative stress levels in noise-induced hearing loss." (PMID 32235401, 2020). "In our study, we found that wild-type SLC26A4 significantly activated, while SLC26A4 mutants inhibited the PI3K/Akt/mTOR pathway in HEK-293T cells, suggesting that this pathway may be another important mechanism of SLC26A4 mutants in hearing loss." (PMID 36072472, 2022). "Further analyses with more cases are needed to evaluate indication of early implementation of SRT with eliglustat as well as indication of mTOR inhibitors and ABCB1 transporter inhibitors to prevent hearing impairment in GD." (PMID 38974840, 2024). "However, it is still not clear whether mutations in SLC26A4 lead to hearing loss via regulation of the PI3K/Akt/mTOR pathway." (PMID 36072472, 2022).
Hydrocephalus (8 papers, 2013 to 2025). Hydrocephalus is an active distension of the ventricular system of the brain resulting from inadequate passage of CSF from its point of production within the cerebral ventricles to its point of absorption into the systemic circulation. "If they increase in size, they can cause seizures or obstructive hydrocephalus, which is when surgical excision is recommended, although some reports showed that mTOR inhibitors are sufficient for hydrocephalus treatment as well as seizure reduction and control." (PMID 34828788, 2021). "Prior studies have indicated that mTOR inhibitors can be effective in managing SEGA and associated hydrocephalus by reducing tumor size." (PMID 39040610, 2024). "While this report is limited to a single instance and hence its findings cannot be generalized, it highlights the potential limitations of relying solely on mTOR inhibitors for hydrocephalus management in SEGA cases." (PMID 39040610, 2024). "Hydrocephalus caused by SEGA can sometimes be managed based on the concept of obstructive hydrocephalus using mTOR inhibitors, as previously documented." (PMID 39040610, 2024). "Five genes (TRIM71, SMARCC1, PTEN, PIK3C, MTOR) were found to be involved in syndromic forms of hydrocephalus, and three other genes (FMN2, FOXJ1 and PTCH1) to be responsible for severe hydrocephalus with AS stenosis." (PMID 34092257, 2021). "Previous studies have identified quantitative proteomics signatures in post-hemorrhagic hydrocephalus and idiopathic normal pressure hydrocephalus, these finding suggests that TLR4-NF-κB, mTOR, PDGFRα signaling and other pathways play an important role in hydrocephalus." (PMID 36052359, 2022). "This could result in less efficient circulation of cerebrospinal fluid and hydrocephalus, and favor the hypothesis that mTOR inhibition affects hippocampal size due to increased pressure of oversized ventricles." (PMID 23724051, 2013). "Future research should focus on elucidating the precise mechanisms of hydrocephalus in SEGA patients and exploring alternative or adjunctive treatments to mTOR inhibitors." (PMID 39040610, 2024). "Despite the successful reduction of SEGA size with mTOR inhibitor therapy, ventricular enlargement persisted, suggesting that the obstruction of the foramen of Monro is not the sole mechanism of hydrocephalus in these cases." (PMID 39040610, 2024). "Despite reducing the tumor size with the mammalian target of rapamycin (mTOR) inhibitors, ventricular enlargement persisted, indicating that obstructive hydrocephalus due to the foramen of Monro blockage was not the sole mechanism." (PMID 39040610, 2024).
infantile spasms (8 papers, 2017 to 2025). A rare epilepsy syndrome characterized by onset of epileptic spasms in infants between 2 and 12 months of age, and rarely up to 24 months. "The use of mTOR inhibitors was reported in 17.1% of individuals with infantile spasms and 18.1% of individuals with focal seizures between 2010 and 2015." (PMID 34566842, 2021). "A smaller fraction of panel-positive FCD2/HME cases (7/34) with somatic variants in MTOR, PIK3CA, or TSC2 also presented infantile spasms." (PMID 31444548, 2019). "How early can treatment with these drugs be (and, regarding this aspect, it is pertinent to think on a comparison of mTOR inhibition and classical antiepileptic drugs, such as vigabatrin, in early manifestations of the disease, such as infantile spasms)?" (PMID 28386314, 2017). "Abnormal mTOR function may be another explanation for infantile spasms, but mTOR dysfunction is seen in only a subset of the numerous etiologies of infantile spasms, so mTOR pathway dysfunction is not required for infantile spasms to occur." (PMID 28367137, 2017).
Interstitial pneumonitis (8 papers, 2014 to 2024). "Interstitial Pneumonitis (IP) is one of the pulmonary complications associated with mammalian Target of Rapamycin-Inhibitors (mTOR-Is)." (PMID 39533221, 2024). "Together with the loss of E-cadherin expression in the LAM, development of interstitial pneumonitis during rapalogs treatment brought us a question whether aberration mTOR signaling impacts the expression of E-cadherin and EMT." (PMID 24571487, 2014). "An obvious question and concern is whether active site mTOR inhibitors will cause interstitial pneumonitis in humans which has been observed with mTORC1 inhibitors such as rapamycin or everolimus." (PMID 25162417, 2014). "It has previously been reported that as many as one in six patients taking mTOR inhibitors develop reversible interstitial pneumonitis." (PMID 24348843, 2014).
intervertebral disc degeneration (8 papers, 2018 to 2026). "This study investigates the effect of 17β-estradiol (E2) on intervertebral disc degeneration (IVDD) through the p70 S6K1 signaling pathway, downstream of mTOR." (PMID 40546320, 2025).
membranous nephropathy (8 papers, 2012 to 2026). "The therapeutic activity of T. wilfordii triptolide is mediated by the PI3K/AKT/mTOR pathway to alleviate membranous nephropathy." (PMID 39071497, 2024). "Further analysis revealed that the miRNA regulatory network genes may be involved in the development of membranous nephropathy by mTOR, PDGFR-β, LKB1, and VEGF/VEGFR signaling pathways." (PMID 34824764, 2021).
metastasis (8 papers, 2011 to 2025). The spread or migration of cancer cells from one part of the body (where they first appeared) to another. "In summary, we first report that the statistically significant upregulation of SNAIL and mTOR were an independent risk factor for recurrence of CRC patients with liver metastasis following metastasectomy." (PMID 40566531, 2025). "In addition, our results indicate that patients who have tumors with sarcomatoid features and bone metastasis are more likely to achieve fewer survival benefits from mTOR inhibitor therapy." (PMID 29108268, 2017). "mTOR inhibitors decreased VEGFC/D expression and diminished lymphangiogenesis and lymph node metastasis in various cancer models." (PMID 33128283, 2021).
mood disorder (8 papers, 2018 to 2025). A cognitive disorder a disturbance in which the person's mood is hypothesized to be the main underlying feature. "Subsequently, we analyzed the activation of mTOR signaling-related proteins in the mPFC, amygdala, and hippocampus (regions implicated in mood disorders) by western blotting." (PMID 39643691, 2025). "Inhibition of the mTOR pathway can lead to changes in affective behaviors in animals, whereas enhancing mTOR activity can be therapeutic to some models of mood disorders." (PMID 36045116, 2022). "Little is known, however, regarding the role of mTOR as a potential link between circadian disruption and the pathogenesis of mood disorders." (PMID 36045116, 2022). "Moreover, as explained in the Introduction, FBXW7 modulates some pathways that play a role in mood disorders, including neurogenesis, mTOR, DISC, and PGC-1α." (PMID 35055338, 2022). "Therefore, mTOR is an emerging signaling pathway of interest in mood disorders pathophysiology and treatment." (PMID 36045116, 2022). "Aberrations in neurogenesis, mTOR, DISC, PGC-1α are thought to play a role in neuroprogressive mental disorders, including mood disorders." (PMID 35055338, 2022).
myopia (8 papers, 2019 to 2025). "In a recent study based on 1347 Chinese adolescents with myopia, single-nucleotide polymorphisms (SNPs) of mTOR were found to be closely related to myopia." (PMID 40990868, 2025). "Gene polymorphisms of MTOR has been shown to be highly connected with myopia severity." (PMID 40110040, 2025). "Other reports have discussed associations between the mTOR gene polymorphisms and myopia." (PMID 40990868, 2025). "They found that polymorphisms in the mechanistic target of rapamycin kinase (MTOR) and platelet-derived growth factor receptor alpha (PDGFRA) genes were associated with different degrees of myopia severity." (PMID 40657400, 2025). "The top pathways associated with both baseline refractive development and susceptibility to myopia were EIF2 signaling, protein kinase A signaling, regulation of eIF4 and p70S6K signaling, mTOR pathway, HIPPO pathway, and axonal guidance signaling." (PMID 31362747, 2019). "In addition, Li reported that PI3K/AKT/mTOR signaling participates in the insulin-mediated regulation of pathological myopia-related factors in retinal pigment epithelial cells." (PMID 40216914, 2025). "In summary, our study suggested that insulin acted on RPE cells as a primary signal molecule, and then increased the cell viability and promoted the secretion of pathological myopia-related factors, which was accompanied by the ultrastructure alteration, through PI3K/AKT/mTOR signaling pathway." (PMID 34001063, 2021).
parasitic infection (8 papers, 2015 to 2023). "The phosphorylation levels of various molecules in the PI3K/AKT/mTOR pathway after parasite infection and antigen stimulation were also detected." (PMID 31727141, 2019). "HICA can also improve muscle recovery by inducing an increase in protein synthesis through mTOR signalling, which also regulates the innate immune response to bacterial, fungal or parasitic infection." (PMID 29267346, 2017). "In addition, the PI3K/AKT/mTOR pathway was activated after parasite infection and antigen stimulation, and the activation of this pathway was suppressed by pre-treatment with an AKT/mTOR inhibitor." (PMID 31727141, 2019).
pleural mesothelioma (8 papers, 2013 to 2024). A neoplasm that arises from the mesothelial cells of the pleura. "The main five enrichment pathways for Wiki were MAPK signaling pathway, PI3K Akt signaling pathway, focal adhesion PI3K Akt mTOR signaling pathway and pleural mesothelioma." (PMID 38736875, 2024). "The mTOR (mechanistic Target of Rapamycin) inhibitor everolimus has been tested in pleural mesothelioma patients in the phase II clinical trial SWOG S0722." (PMID 38136262, 2023). "A second study tested the selective dual PI3K/mTOR inhibitor LY3023414 (samotolisib) in 42 patients affected by relapsed pleural mesothelioma." (PMID 38136262, 2023). "Consistent results had been obtained on both DMPM and pleural mesothelioma cell lines where the antiproliferative effect of combined mTOR and PI3K inhibition was stronger than that induced by single agents." (PMID 31752449, 2019). "Epithelioid-type pleural mesothelioma cells show activation of PI3K/AKT/MTOR signaling." (PMID 28191281, 2016). "In vivo, F-FDG uptake in pleural mesotheliomas shows high correlations with GLUT1, HIF1, VEGF, CD34, Ki67, and MTOR upregulation, and poor patient prognoses." (PMID 28191281, 2016). "The inactivation of NF2 in malignant Pleural Mesothelioma with mTOR activity aberrantly upregulated, fails to inhibit cell proliferation, leading to a poor prognosis." (PMID 32723974, 2020).
prostate (8 papers, 2011 to 2025). "In this study, we first elucidated the mechanism against chronic prostatitis that phenolamides from bee pollen involve the activation of autophagy via the AMPK/mTOR pathway." (PMID 40552335, 2025).
renal failure (8 papers, 2015 to 2025). "As expected, mTOR was more frequently prescribed to patients with renal insufficiency (91.6% for HRS1, 78.9% for HRS2, 86.0% for CKD, and 38.8% for the reference group, P < 0.001)." (PMID 37077866, 2023).
tendinopathy (8 papers, 2020 to 2025). "al, screening for biomarkers of tendinopathy revealed common processes dysregulated in tendinopathy were related to the cell cycle, mitochondria function and pro-inflammatory responses as well as mTOR and NF-κB signaling pathways." (PMID 39975248, 2025). "In the tendon tissues, mTOR signaling pathway has been reported to participate in the senescence and tendinopathy." (PMID 35197108, 2022). "Based on these results, we assessed the preventative potential of the classic mTOR antagonist rapamycin in the prevention of tendinopathy development due to excessive mechanical loading." (PMID 34322484, 2021). "Further studies in vivo are needed to confirm the involvement and corresponding mechanisms of mTOR signaling and autophagy in the prevention of aging-induced tendinopathy." (PMID 33603790, 2021). "The mRNA expression of mTOR was suppressed in human tendinopathy samples, compared to normal tendon tissues, suggesting that deficiency of mTOR might be related to the pathogenesis of tendinopathy." (PMID 35408931, 2022). "Second, mTOR is known to be linked to aging-associated tendon disorders, and future studies may include mice of different ages in the ITR model to further elucidate the role of mTOR and the effects of rapamycin in the development of tendinopathy." (PMID 34322484, 2021). "In this study, we investigated whether mechanical loading could activate the mTOR signaling in TSCs and explored whether inhibiting mTOR by rapamycin could prevent tendinopathy development due to mechanical overloading placed on the tendon." (PMID 34322484, 2021). "Thus, nesfatin-1 promotes the osteogenic differentiation of TDSC and the pathogenesis of HO in rat tendons via the mTOR pathway; these findings highlight a new potential therapeutic target for tendinopathy." (PMID 33344440, 2020). "Based on the findings from the in vitro study, we suggest that mTOR signaling in PTSCs plays a critical role in the development of degenerative tendinopathy due to mechanical overloading in ITR mice, and that as a specific inhibitor of mTOR, rapamycin may be used to prevent tendinopathy development." (PMID 34322484, 2021). "Mechanical overloading activated the mechanistic target of rapamycin (mTOR) pathway, which can lead to non-tenocyte differentiation and contribute to tendinopathy." (PMID 40948974, 2025). "Collectively, these findings suggest that mechanical loading activates the mTOR signaling in TSCs, and rapamycin may be used to prevent tendinopathy development by blocking non-tenocyte differentiation due to mechanical over-activation of mTOR in TSCs." (PMID 34322484, 2021).
Ureteral obstruction (8 papers, 2012 to 2025). Obstruction of the flow of urine through the ureter. "Besides, autophagy substantially reduced renal inflammation and interstitial damage in a unilateral ureteral obstruction (UUO) model where mTOR inhibition significantly increased autophagy and suppressed UUO-induced inflammation." (PMID 34938183, 2021). "This was evident as in a mouse model of unilateral ureteral obstruction (UUO), where rapamycin treatment ameliorated kidney fibrosis by directly inhibiting mTOR signaling in myofibroblasts and interstitial macrophages." (PMID 34065421, 2021). "The gene expression involved in the mTOR signaling pathway and autophagy was assessed in TGF-β1-treated human renal tubular epithelial cells (HK-2) and unilateral ureteral obstruction (UUO) mice before and after MSC-derived exosomes and miRNA-122a mimic treatment." (PMID 35859725, 2022).
viral myocarditis (8 papers, 2019 to 2024). Myocarditis that is caused by an infection with a viral agent. "In this study, we investigated whether CPCs-derived exosomes (CPCs-Ex) could utilize the mTOR signal pathway to reduce the apoptosis in viral myocarditis." (PMID 31534118, 2019).
vitiligo (8 papers, 2021 to 2025). Generalized well circumscribed patches of leukoderma that are generally distributed over symmetric body locations and is due to autoimmune destruction of melanocytes. "The PI3K/Akt/mTOR pathway is vital for protection against oxidative stress often associated with the pathogenesis of vitiligo." (PMID 37371141, 2023). "Collectively, in the vitiligo cells, the basal activation of mTOR, the high level of phosphorylated S6, and poor inducibility by insulin reflected in low Akt phosphorylation fully correspond to the description of cellular IR." (PMID 40277891, 2025). "Modulation of the PI3K/AKT/mTOR signaling pathway could offer a novel approach for managing vitiligo according to our study." (PMID 40837640, 2025). "Interestingly, although persistent activation of AMPK is a common trait of vitiligo cells, there was also a modest but recurrent upregulation of mTOR and p-mTOR even though AMPK is a known inhibitor of mTOR." (PMID 40277891, 2025). "Thus, αMSH activates the PI3K/Akt/mTOR pathway, and its inhibition can protect against and treat vitiligo via protecting against ROS-induced oxidative stress." (PMID 37371141, 2023). "The mTOR pathway is also involved in melanocyte survival in response to UV radiation and oxidative stress and its modulation is thought to offer better approaches for the clinical management of vitiligo." (PMID 34501405, 2021).
alcoholic liver diseases (7 papers, 2018 to 2025). A disorder caused by damage to the liver parenchyma due to alcohol consumption. "KEGG pathway analysis demonstrated that DEFRGs after sevoflurane exposure were main involved in ferroptosis, mTOR signaling pathway, longevity regulating pathway, circadian rhythm, and alcoholic liver disease." (PMID 36238640, 2022). "Among which, 19 upregulated FRGs were mainly involved in alcoholic liver disease, mTOR signaling pathway, and glycerolipid metabolism, while 18 downregulated FRGs were mainly involved in ferroptosis, central carbon metabolism in cancer, and longevity regulating pathway." (PMID 36238640, 2022).
Angelman syndrome (7 papers, 2018 to 2024). A neurogenetic disorder characterized by severe intellectual deficit and distinct facial dysmorphic features. "We recently reported that LAMTOR1 is a target of the UBE3A ubiquitin ligase, which is downregulated in Angelman syndrome (AS), thereby implicating changes in lysosomal distribution, function and mTOR signaling in the etiology of AS." (PMID 39650798, 2024).